CD44 (CD44 molecule (IN blood group))
Diseases named in the same sentence as CD44 in open-access papers (continued):
Sharing a sentence is not in itself a finding about the gene and the disease.
tumor (continued). "CD44 is involved in a number of important biological processes including lymphocyte activation and homing, hematopoiesis, and tumor progression, and metastasis." (PMID 24381635, 2013). "The stem cell marker CD44 is expressed in PCa selectively in NE tumor cells, indicating that these cells are endowed with stem cell properties." (PMID 22229096, 2012). "The proportions of CD44+/CD24- tumor cells in clinical specimens correlated significantly with lymph node involvement (P = 0.026) and PR expression (P = 0.038)." (PMID 22762532, 2012). "Image analyses of 10 slices obtained from three tumors revealed significantly higher CD44 antibody localization in hypoxic tumor regions." (PMID 22937154, 2012). "On the other hand, another study reported that CD44+/CD133+ cells were enriched with tumour-initiating characteristics." (PMID 22693526, 2012). "While there appears to be significant overlap between CD133 positive and CD44+/CD24+ cells, this overlap appears to vary between different tumor samples with only 10 to 40% of the CD44+/CD24+ cells expressing CD133." (PMID 22570653, 2012). "VACV GLV-1h68 strain shows higher replication in GI-101A derived CD44+CD24+ESA+ cells resulting in increased eradication of CD44+CD24+ESA+ cells derived tumor xenografts." (PMID 22901246, 2012). "The proportion of CD133+ and CD44+ tumor cells varied greatly between models, consistent with the wide variation in the proportion of positive cells between tumors noted in the original publications identifying each of these CSC markers." (PMID 23115623, 2012). "CD44 when overexpressed in HNSCC characterises tumours with good differentiation, increased proliferation rate and resistance to accelerated radiotherapy." (PMID 22333601, 2012). "We found that a significantly higher proportion of secondary than primary lesions were positive for CD44+/CD24-/low tumor cells (26.9% versus 7.0%, P < 0.05)." (PMID 22762532, 2012). "Work by Prince and colleagues in 2007 was the first to identify a subpopulation of HNSCC tumor cells with stem cell-like phenotypes, initially using the cellular marker CD44." (PMID 22876238, 2012). "Injection of CD44/Sca1+ tumor cells resulted in the detection of 4.99 ± 0.5%, 1.77 ± 0.3%, and 3.56 ± 0.9% GFP and ESA double positive (GFP/ESA+) cells in the blood, LN and lungs, respectively, of recipient mice." (PMID 22277639, 2012). "In the H441 model, there was a robust increase in CSC marker positive tumor cells with a ∼3-fold increase in CD44+ cells, a 12.5-fold increase in CD133+ cells and a 5-fold increase in CD117+ cells." (PMID 23115623, 2012). "After 3 weeks continuous treatment with DTX, obvious tumor growth regression was found in CD44- or CD147-KD mice compared with the controls." (PMID 22870202, 2012). "CD147, through interactions with HA receptors (CD44) and membrane-bound transporters, facilitates tumor cell chemoresistance." (PMID 22870202, 2012). "To analyze the effect of GSI on proliferation of pancreatic CD44+/EpCAM+ cells in xenograft tumors we performed Ki67 staining of xenograft tumor tissues." (PMID 23094026, 2012). "The normal and neoplasm groups showed increased expression of CD44 for between five and six probes, respectively, whereas decreased expression of CD44 was found for five out of six probes in the disease and cell line groups." (PMID 22242150, 2012). "The intensity of immunohistochemical staining of CD44, CD147, CD31, Ki-67, Caspase-3(active), TUNEL in tumor xenografts from PC-3M-luc, PC-3M-luc-scr, PC-3M-luc-CD44-KD and PC-3M-luc-CD147-KD with DTX and/or veihicle treatment." (PMID 22870202, 2012). "Recently, a subpopulation of tumor cells has been identified in HNSCC based on the overexpression of the cellular marker CD44 and increased activity of aldehyde dehydrogenase." (PMID 22876238, 2012).
tumor (continued). "Studies have shown that miR-34a is down regulated in CD44+ PCa cells, and its forced expression in CD44+ PCa cells resulted in the inhibition of clonogenic growth and inhibition of metastatic behavior and tumor regeneration." (PMID 22417299, 2012). "Specifically, the CD49f+/CD44+/CD133hi population identified tumor cells with enriched sphere-forming and xenografting potential." (PMID 22225988, 2012). "Further investigation on the relationship between the CD44+CD24-/low expression of tumor cells and LN metastases is warranted." (PMID 23046710, 2012). "Histological examination showed that these tumors were positive for GFP and that some tumor cells were also positive for CD44." (PMID 22277639, 2012). "This means that quantitative evaluation of not only CD44 “in general”, but even of v3/v6-containing isoforms are inappropriate for the prognosis of metastatic behavior of a single tumour case because of the summative way of the measurement techniques." (PMID 23151220, 2012). "We finally identified and sorted the CD44/Sca1+ cells from mammary epithelial/tumor cells of MMT mice at premalignant and malignant stages of tumorigenesis." (PMID 22277639, 2012). "CD44 plays a major role in myriads of physiological processes and is particularly important in malignancy, in tumor cell homing and metastasis." (PMID 22216413, 2012). "Carcinoma of the intestinal type are more frequently CD44s and CD44v6 positive than carcinomas of the diffuse type, and the importance of subclassifying tumor types in investigations of CD44 in human cancer has been demonstrated." (PMID 22839505, 2012). "Of interest, all five recurrent tumours overexpressed CD44 (P=0.14), and Oct4 (P=0.01) and 4/5 overexpressed integrin-β1 (P=0.04)." (PMID 22333601, 2012). "These tumour-initiating cells were distinguished from a substantially larger, non-tumourigenic cell population by the specific cell surface marker phenotype CD44+/CD24−." (PMID 23028444, 2012). "Further investigations were performed on EPCAM, VEGFR and CD44, tetraspanins and integrins previously reported to participate in tumor progression by preparation of (pre)metastatic niche." (PMID 22768192, 2012). "The proportion of CD44+/CD24-/low tumor cells (P = 0.002), PR status (P = 0.004), basal-like feature (P = 0.007), and TNM stage (P = 0.029) were strongly correlated with DFS." (PMID 22762532, 2012). "We then compared the CD44 pattern of the primary tumour and the liver metastasis/colony of the same animal in both models." (PMID 23151220, 2012). "Through comprehensive characterization of the NPC spheroids, tumor lines and primary tumor, we have revealed that CD44 and SOX2 are potential CSC markers for NPC." (PMID 23285037, 2012). "The tumor promoting as well as tumor initiating potential of CD44 has been observed in many cancers." (PMID 23056490, 2012). "Consistent with its role in promoting CD44-mediated migration and invasion, a number of studies have demonstrated that inhibition of HA production results in suppression of in vivo tumour development and metastasis." (PMID 23039365, 2012). "Similar trends were observed in a 99.9% CD44 positive stem cell culture derived from a fresh HNSCC tumor, confirming our findings for the cell lines." (PMID 22384257, 2012). "It is thought that hyaluronan provides increased barrier integrity and chemoresistance through CD44-dependent reorganisation of the tumour cytoskeleton, where as the anti-CD44 monoclonal antibody IM7 (anti-CD44 IgG2b mAb IM7) improves vascular permeability." (PMID 23125850, 2012). "Our data here show here that acquisition of tamoxifen resistance results in the overexpression of CD44 which augments the cells’ sensitivity to ligands commonly found within the tumour microenvironment." (PMID 23039365, 2012). "Several stem cell markers (CD133, CD44, Sca1) have been used successfully to isolate stem cells in normal and tumor tissue." (PMID 22272227, 2012).
tumor (continued). "A theory is emerging that CD44 positive cells within a tumor display true stem cell properties such that one cell can give rise to an entire tumor." (PMID 23213537, 2012). "The cell surface proteoglycan CD44 is overexpressed on a variety of tumor cells, and cells with higher expression of CD44 have a greater migratory and invasive potential on hyaluronate-coated substrates." (PMID 23213537, 2012). "By 22 weeks after implantation, the tumor size had reached 700 mm3 in volume in contrast to 200 mm3 of tumors derived from CD44+CD24-ESA+ cells." (PMID 22901246, 2012). "We finally identified a subpopulation of mammary epithelial/tumor cells expressing CD44 and Sca1 that was largely responsible for dissemination and metastasis in MMT mice." (PMID 22277639, 2012). "In agreement with the CSC definition, CD44+CD24+ESA+ cells were able to give rise to a heterogeneous tumor cell population, with the expression patterns of CD44, CD24, and ESA resembling that of the primary tumor." (PMID 24213498, 2012). "5/15 models ranged between 6.3% and 15.8%, whereas the largest subgroup (eight tumour models) exhibited < 5% CD44 expression." (PMID 22433494, 2012). "Simeone similarly used CD24/CD44/EpCAM to identify a pancreatic CSC population that displayed the ability to form tumor cell spheres as well as enhanced tumor formation in nude mice." (PMID 22570653, 2012). "This indicated that the tumor-initiating, self-renewing cancer cells were concentrated in the CD44-positive fraction." (PMID 23155468, 2012). "CD44, a hyaluronic acid receptor, is one of the most commonly studied surface markers, which is expressed by almost every tumour cell." (PMID 22693526, 2012). "Data from these cell studies were further supported by in vivo observations that hypoxic tumor regions contained cells with a higher concentration of CD44 expression." (PMID 22937154, 2012). "Our findings indicated that CD44 or CD147-KD with VC treatment strongly regressed tumor progression for at least 8 weeks." (PMID 22870202, 2012). "CD147 stimulates production of HA, an extracellular polysaccharide that promotes tumor chemoresistance through interactions with the cell surface receptor CD44." (PMID 22870202, 2012). "Clinical studies have also confirmed the enrichment of CD44 expression in disseminated tumor cells resident in secondary tissue sites." (PMID 22621373, 2012). "The results show that anti-miR-21 decreased the expression of CD44 and EpCAM in MiaPaCa-2 tumor sphere cells under hypoxic conditions, consistent with the results from CDF treatment." (PMID 23272057, 2012). "CDF treatment decreased the relative mRNA levels of HIF-1α, VEGF, IL-6, CD44, and EpCAM in MiaPaCa-2 tumor sphere cells under hypoxic conditions." (PMID 23272057, 2012). "The interaction between HA and CD44 has been shown to trigger pathways related to tumor growth and survival." (PMID 22870202, 2012). "We first determined the percentage of activated T cells after tumour challenge, by measuring the frequencies of CD44+ and CD62Llow cells." (PMID 22506061, 2012). "The cell adhesion receptor CD44 has been shown to be expressed on the surface of tumour initiating cells in solid tumours of the breast, pancreas, prostate and squamous cell carcinomas of the head and neck (SCCHN)." (PMID 23071680, 2012). "Hyaluronan-rich stroma is associated with poor prognosis in many epithelial cancers including pancreatic and together with CD44 promotes tumour cell growth, migration, and metastases." (PMID 23125850, 2012). "Lastly, the enhanced viral replication in the tumor xenograft derived from cancer stem-like ALDH1+CD44+CD24+ESA+ cell implantation led to a more efficient elimination of tumors, in comparison to ALDH1-CD44+CD24-ESA+ cell derived xenografts." (PMID 22901246, 2012). "We observed that a subpopulation of tumor cells in all the samples showed dual expression of EpCAM with CD44, CD24 and ABCG2 individually." (PMID 22328825, 2012).
tumor (continued). "ALDHhi CD44+ CD24− breast tumor cells were capable of tumor initiation when as few as 20 cells were injected into NOD/SCID mice." (PMID 22295241, 2012). "In this role, CD44 facilitates tumor progression through the MAP kinase and PI3 kinase/AKT signaling cascades, which subsequently increase cancer cell invasion, growth, motility, and survival." (PMID 23155468, 2012). "A complex preclinical experimental set-up was established to separately test the different steps of tumour progression and the role of tumour microenvironment, respectively, focusing on the role of ‘CD44’ in this process." (PMID 23151220, 2012). "However, while CD44 was definitely linked with GC in our study and prognostic to some degree, we could not verify its predictive capability in terms of GC recurrence after tumor resection." (PMID 22839505, 2012). "We found that CD133+ and CD44+ populations were enriched in tumor spheroids from OVCAR3 and TOV112D cells." (PMID 22643117, 2012). "Recently, it has been suggested that E-cadherin repression and CD44 expression are associated with the epithelial-mesenchymal transition (EMT), which was thought to lead to tumor invasion." (PMID 22225786, 2012). "This makes the development of CD44-targeted drugs important as few therapeutics are capable of killing 100% of the cells within a tumor." (PMID 23213537, 2012). "It was shown that Prostate CSCs that have increased clonogenic potential, and tumor initiating ability and metastasis capacities, have increased CD44+ cell population." (PMID 22417299, 2012). "It is well noted that tumor cells with CD44+CD24-/low expression not only possess malignant behavior as other tumor cells, but also share with normal stem cells the capacity for self-renewal." (PMID 23046710, 2012). "Higher proportions of CD44+/CD24- tumor cells were observed in specimens from patients with (19.20%) than without (8.66%) lymph node involvement and with (21.06%) than without (13.09%) PR expression." (PMID 22762532, 2012). "We assessed the role of Notch for the maintenance of tumor initiating pancreatic CD44+/EpCAM+ cells and found that with down regulation of the Notch signalling pathway the expression of CD44 and EpCAM on protein level were dramatically decreased." (PMID 23094026, 2012). "We also performed apoptotic assay in these sorted tumor initiating CD44+/EpCAM+ cells in order to study the mechanism by which GSI IX treatment affects cell growth." (PMID 23094026, 2012). "Regulation of CD44 or CD24 expression in various cancers seems to be effective in controlling tumour initiation and inhibition of CSC population." (PMID 22693526, 2012). "The Stamenkovic and Seiki laboratories also reported that CD44 can complex with secreted and membrane-tethered matrix metalloproteinases, localizing their proteolytic activity to the invasive edge of tumor cells." (PMID 22621373, 2012). "Disruption of the hyaluronan-CD44 interaction is a key therapeutic target to prevent tumour refractoriness secondary to drug resistance." (PMID 23125850, 2012). "CD44 plays a major role in cell-cell adhesion, cell-substrate interaction, lymphocyte homing, and tumor metastasis." (PMID 23112867, 2012). "CD44 is a transmembrane adhesion molecule acting as the receptor for hyaluronan, a major component of the tumor extracellular matrix." (PMID 23227266, 2012). "The prevalence of CD44+/CD90+/cytokeratin+ cells in primary tumor was intermediate between normal lung and MPE, with a distinct cluster of 3 high prevalence tumors." (PMID 23285214, 2012). "Quantification of CD44+/CD24− cancer cells showed that this population was present in 51/56 (91%) tumours examined; the median population fraction was 6.12% (range, 0.11–21.23%)." (PMID 23028444, 2012).
tumor (continued). "At the end of experiments, TUNEL-positive tumor cells from PC-3M-luc-CD44-KD (28–35/ hpf) and PC-3M-luc-CD147-KD (30–36/ hpf) xenografts in DTX-treated groups displayed typical apoptotic cell morphology with nuclear chromatin condensation and fragmentation." (PMID 22870202, 2012). "Enhanced tumorigenicity of marker expressing cells was confirmed by orthotopic implantation of CD44+CD24+ESA+ versus CD44−CD24−ESA− cells in NOD/SCID mice, with tumor forming potential being 100 fold higher in CD44+CD24+ESA+ cells." (PMID 24213498, 2012). "In vitro, CD44-positive tumour cells display self-renewal properties indicative of stem cell behaviour." (PMID 23071680, 2012). "In a univariate analysis, the patients with “high” CD44+/CD24− tumours displayed a shorter median MFS (18 months) than those with “low” CD44+/CD24− tumours (median MFS not reached; p = 0.004)." (PMID 23028444, 2012). "When all predictors were included in a Cox model (multivariate analysis), the presence of CD44+/CD24-/low tumor cells (hazard ratio, 2.237; P = 0.002), basal-like feature, and TNM stage retained their prognostic significance for OS." (PMID 22762532, 2012). "To determine the proportion of tumorigenic CD44+/CD24- cells within each tumor, we scanned for the presence of permanent red staining without any diaminobenzidine interference." (PMID 22762532, 2012). "This is based on the roles of CD44 and Oct-4A in defining TICs, on the motility/invasivity of vimentin-rich tumor cells, and on the expression of CAF markers α-SMA and PDGFβ-R." (PMID 22901285, 2012). "When all predictors were included in a Cox model (multivariate analysis), the presence of CD44+/CD24-/low tumor cells (hazard ratio, 1.931; P = 0.011), PR status, basal-like feature, and TNM stage retained their prognostic significance for DFS." (PMID 22762532, 2012). "Despite hundreds of published studies on CD44 within the last two decades, noconsensus opinion has been reached as of today apart from that it plays some role in tumour progression." (PMID 23151220, 2012). "Tumor volumes at the end of experiment in the CD44 or CD147-KD mice decreased by 37% and 35% respectively compared with the scr-controls." (PMID 22870202, 2012). "CD44 is the major hyaluronan receptor and is important for the homing and settling of adult stem cells, metastasizing tumour cells and cancer initiating cells." (PMID 22433494, 2012). "To further determine the effect of GSI on sorted tumor initiating CD44+/EpCAM+ cells, we analyzed the effect of GSI by cell proliferation assay." (PMID 23094026, 2012). "There was a positive association of amplification of ERBB4 (OR = 2.62, 95% CI = 1.23–5.59, P < 0.05) and CD44 (OR = 2.28, 95% CI = 1.08–4.79, P < 0.05) with tumor differentiation." (PMID 22606006, 2012). "In vivo, CD44 or CD147-KD PC-3M-luc xenografts displayed suppressed tumor growth with increased DTX responsiveness compared to control xenografts." (PMID 22870202, 2012). "Further, the relationship between CXCR4 and tumor initiating cell markers CD133/CD44 is reciprocal: CXCR4+ cells have a higher percentage of CD133+/CD44+ than CXCR4− cells and CD133+/CD44+ cells contain more CXCR4+ cells than CD133−/CD44− cells." (PMID 22359577, 2012). "The expression of human CD44 was pronounced in all tumour cells in controls and appeared to be redistributed and upregulated after 4-MU treatment in the tumour cells that faced the stromal tissue (right)." (PMID 21429221, 2011). "Our systematic studies in xenograft models indicate that PCa cells are heterogeneous with respect to their tumor-initiating capacity with the CD44+ cell population harboring both quiescent CSCs and fast proliferating tumor progenitors." (PMID 21935404, 2011). "Attempts to link CD44 to CSCs and tumor development should consider the expression of various CD44 isoforms." (PMID 21957977, 2011).